CCNB2 (cyclin B2)
Diseases named in the same sentence as CCNB2 in open-access papers (continued):
Sharing a sentence is not in itself a finding about the gene and the disease.
hepatocellular carcinoma (18 papers, 2020 to 2025). A malignant tumor that arises from hepatocytes. "For instance, overexpression of CCNB2 is associated with poor prognosis in hepatocellular carcinoma (HCC), and reduced expression of this gene can suppress the metastasis and invasion of bladder cancer." (PMID 41049007, 2025). "For one of the subfamilies, CCNB2 has been verified to be significantly associated with tumor number, tumor size, tumor thrombus, and alanine aminotransferase level in patients with hepatocellular carcinoma." (PMID 38166895, 2024). "Several researches showed that CCNB2 overexpression was associated with poor prognosis in human hepatocellular carcinoma, non-small cell lung cancer patients and invasive breast carcinoma." (PMID 33408743, 2020). "Interestingly, treatment with TA attenuated MSG-induced upregulation of Aurora kinase A (Aurka) and Cyclin B2 (Ccnb2), and downregulation of Coagulation Factor IX (F9) and Cytochrome P450 2E1 (Cyp2e1) gene expressions, in which these genes are hepatocellular carcinoma-associated key genes." (PMID 39925850, 2025). "CCNB2 was also overexpressed in human hepatocellular carcinoma (HCC) tissues and associated with the poor prognosis." (PMID 34354775, 2021). "CCNB2 suppression has been shown to induce cell cycle arrest, reduce proliferation, and promote apoptosis in multiple cancer models (e.g., hepatocellular carcinoma)." (PMID 41301480, 2025). "High CCNB1, CCNB2, and CDK1 expression has been associated with inferior prognosis in hepatocellular carcinoma patients." (PMID 38102624, 2023). "CCNB2 may accelerate the proliferation and migration of human hepatoma cells and inhibit their apoptosis." (PMID 35349480, 2022). "In hepatocellular carcinoma, CCNB2 may serve as a prognostic factor and participate in tumor development and progression by promoting cell proliferation and migration." (PMID 33937050, 2021). "Upon reviewing the literature, it is evident that CCNB2 expression in hepatocellular carcinoma (HCC) demonstrates a significant correlation with KPNA2, implicating its involvement in mitotic and cell cycle regulatory processes, thereby exerting a substantial impact on HCC progression." (PMID 39100078, 2024). "Furthermore, CCNB2, MAD2L1, BUB1, and NCAPG are significantly upregulated in hepatocellular carcinoma (HCC) tissues and are implicated in the growth and metastasis of HCC cells." (PMID 32265985, 2020).
prostate carcinoma (18 papers, 2018 to 2025). A carcinoma that arises from epithelial cells of the prostate gland. "When circ_CCNB2 is knocked down, it suppresses the colony formation and metastatic ability of radioresistant prostate cancer cells while promoting apoptosis." (PMID 41049007, 2025). "Here, we establish the first disulfidptosis-based molecular subtyping framework for prostate cancer (PCa) and identify CCNB2 as a novel regulator of disulfidptosis, revealing its dual role in apoptosis activation and immune microenvironment remodeling." (PMID 41049007, 2025). "We had demonstrated through CCK8, scratch, and transwell invasion assays that the knockdown of CCNB2 inhibited the proliferation, migration, and invasion capabilities of prostate cancer." (PMID 41049007, 2025). "Through immunohistochemistry, we demonstrated that there was indeed a difference in CCNB2 expression between prostate cancer tissue and benign prostatic hyperplasia." (PMID 41049007, 2025). "In inducing the radio-resistance feature of prostate cancer cells, circ-CCNB2 downregulates the expression level of MIR30B-5p via sponging." (PMID 35317831, 2022). "The close relationship between the high expression of CCNB2 and the poor prognosis of liver cancer and prostate cancer stimulated our interest in its role in LGG." (PMID 34908101, 2022). "The circRNA CCNB2 (cyclin B2) undergoes upregulation in prostate cancer and its silencing promotes sensitivity to irradiation." (PMID 35317831, 2022). "Finally, our experimental results confirmed that downregulation of CCNB2 expression promoted disulfidptosis in prostate cancer cells, thereby inhibiting their migration and proliferation capacities." (PMID 41049007, 2025). "Furthermore, the CCNB2 gene emerges as a potential therapeutic target for prostate cancer by regulating disulfidptosis, thereby influencing the biological behaviors of PCa cells, including their proliferation and migration." (PMID 41049007, 2025). "At the therapeutic level, inhibition of circ-CCNB2 may have a radiosensitizing effect to improve RT efficacy in patients with recurrent prostate cancer." (PMID 36142355, 2022). "Prostate tumors: circ-CCNB2 may predict the development of radioresistance in prostate cancer RT." (PMID 36142355, 2022). "It was proved that the knockdown of circ_CCNB2 increased the radiosensitivity of PCa through repressing autophagy by the miR-30b-5p/KIF18A axis, but no biological function of CCNB2 in prostate cancer has been found." (PMID 35360870, 2022).
liver cancer (11 papers, 2017 to 2026). An epithelial or non-epithelial malignant neoplasm that arises from the liver. "The data presented indicate that Anln, Hmmr, Tpx2, Ccnb1, and Ccnb2 may be influenced by changes in miR-122 expression and potentially contribute to liver cancer development." (PMID 37566034, 2023). "CCNB2 may responsible for the initiation and progression of liver cancer through the CCNB2/PLK1 pathway and increase the growth and migration of liver cancer cells." (PMID 34838000, 2021). "The top modular genes, TOP2A, CDC20, PRC1, CCNB2, and NUSAP1, were highly associated with HCC onset and development; high expression of TOP2A, CDC20, or CCNB2 was correlated with poor survival time in TCGA liver cancer patients, implying their potential as biopsy-based prognostic markers." (PMID 31001331, 2019). "In order to explore the mechanism by which CDKN3 influences the occurrence and development of liver cancer, we used bioinformatics tools to screen genes related to changes in CDKN3, and SPC25, CDK1 and CCNB2 were identified." (PMID 32000807, 2020). "Notably, and in agreement with what was observed in the mouse models of liver cancer, ANLN, HMMR, TPX2, CCNB1, and CCNB2 expressions were found to be significantly upregulated in TCGA-LIHC." (PMID 37566034, 2023).
bladder cancer (10 papers, 2017 to 2025). "Besides, high CCNB2 expression is associated with a poor prognosis in other organ tumors such as breast and bladder cancer." (PMID 35859798, 2022). "CCNB2 has been shown to be highly expressed in a range of human cancers, such as lung cancer, bladder cancer, nasopharyngeal cancer, and liver cancer." (PMID 38300330, 2024). "In this study, high expression of CCNB2 was also found to regulate the progression of oral and bladder cancer." (PMID 36820589, 2023). "The main result of this study was that CCNB2 was highly expressed in oral and bladder cancer, and the higher the CCNB2, the worse the prognosis." (PMID 36820589, 2023). "Although the value of CCNB2 in oral cancer and bladder cancer was analyzed with the help of the database, there are some limitations in the current study." (PMID 36820589, 2023). "For example, the overexpression of CCNB2 is associated with poor prognosis of HCC, while the decreased expression of CCNB2 inhibits the invasion and metastasis of bladder cancer." (PMID 34908101, 2022). "In summary, CCNB2 was one common oncogene of bladder cancer and OSCC." (PMID 36820589, 2023). "And CCNB2 was upregulated in oral cancer and bladder cancer, which might be one potential biomarker of the 2 cancers." (PMID 36820589, 2023). "However, cyclin B2 overexpression was a poor prognostic biomarker in non-small cell lung cancer, bladder cancer, invasive breast carcinoma, colorectal adenocarcinoma." (PMID 28969025, 2017). "Therefore, we speculate that CCNB2 is highly expressed in oral and bladder cancer, promoting the proliferation of tumor cells, and thus worsening the disease." (PMID 36820589, 2023). "Hub genes (CCNB2, CDC20) are highly expressed in OSCC and bladder cancer samples." (PMID 36820589, 2023).
non-small cell lung carcinoma (10 papers, 2017 to 2025). A group of at least three distinct histological types of lung cancer, including non-small cell squamous cell carcinoma, adenocarcinoma, and large cell carcinoma. "CCNB2 is overexpressed in non-small cell lung cancer and is closely associated with poor prognosis." (PMID 34880897, 2021). "A clinical study showed that CCNB2 overexpression is a poor prognostic biomarker in patients with non-small cell lung cancer." (PMID 36589226, 2022). "Some other genes, such as BIRC5, BLM, and CCNB2, are also differentially expressed in non-small-cell lung cancer." (PMID 33346087, 2020). "CCNB2 was found to be overexpressed and then result in poor prognosis in non-small-cell lung cancer and invasive breast carcinoma." (PMID 31043166, 2019). "Consistently, high expression of CCNB2 at the protein level was positively related to the status of differentiation, lymph node metastases, distant metastases, and clinical staging of Chinese patients with non-small cell lung cancer." (PMID 38166895, 2024). "Up-regulation of CCNB2 has a negative effect on the outcome of sufferers with non-small cell lung carcinoma." (PMID 31870357, 2019).
invasive breast carcinoma (9 papers, 2013 to 2022). A carcinoma that infiltrates the breast parenchyma. "CCNB2 expression was also increased in invasive breast carcinoma and associated with unfavorable clinical outcome." (PMID 34354775, 2021). "In invasive breast carcinoma, cytoplasmic CCNB2 protein levels were significantly correlated with a poor disease specific survival." (PMID 30254986, 2018). "Furthermore, CCNB2 was found to be overexpressed in several malignant tumors, and high expression of CCNB2 is associated with poor prognosis in HCC and invasive breast carcinoma." (PMID 36317111, 2022). "In addition, Cyclin B2 has been shown be an independent prognostic biomarker in invasive breast cancer." (PMID 34638823, 2021).
ovarian carcinoma (9 papers, 2009 to 2023). A malignant neoplasm originating from the surface ovarian epithelium. "As validated by a comprehensive bioinformatics study, CCNB2 has been identified as a promising therapeutic target for ovarian cancer." (PMID 35354488, 2022). "Among them, expression of CENPE and CCNB2 correlates with worse clinical outcomes of patients with breast or ovarian cancers." (PMID 26317392, 2015). "Our further qRT-PCR showed that seven hub genes (BUB1, KIF2C, NUP43, NDC80, NUF2, CCNB2 and CENPN) were differentially expressed in platinum-resistant ovarian cancer cells." (PMID 34820170, 2021). "Using real-time PCR, we found that silencing SMYD3 significantly decreased the mRNA levels of CCNA2, CCNB2, CCND2, CDK1 and CDK2 (p<0.05) but increased the mRNA levels of WEE1 (p<0.05), suggesting an essential role for SMYD3 in ovarian carcinoma proliferation." (PMID 31417652, 2019). "In agreement with our results, it has been previously shown that in the OVCAR-3 ovarian cancer cell line, OLE induces cell cycle arrest through a decrease in Cyclin B2, leading to the G2 to M-cell cycle progression, in parallel with an increase in apoptosis-related markers." (PMID 36614279, 2023). "Further, a series of genes, such as cyclin E1 (CCNE1), cyclin B2 (CCNB2), cytochrome P450 family 3 subfamily A member 5 (CYP3A5), and vascular endothelial growth factor A (VEGFA), have been predicted as target genes for diagnosing ovarian cancer." (PMID 29482638, 2018).
pancreatic cancer (8 papers, 2008 to 2025). "In this study, we demonstrated that AR-42 inhibited growth of pancreatic cancer cells in vitro and in vivo, and caused cell cycle G2/M arrest by regulating expression levels of cyclin B1, cyclin B2, CDK1, and p21." (PMID 28829799, 2017). "Eight genes (BUB1, BUB1B, CCNA2, CCNB2, CDC6, CDC20, CDK1, and TTK) among 21 common network genes were correlated with worse survival of pancreatic cancer, highlighted with P-value significantly <0.05." (PMID 32117719, 2020).
acute myeloid leukemia (7 papers, 2021 to 2025). Acute myeloid leukemia (AML) is a group of neoplasms arising from precursor cells committed to the myeloid cell-line differentiation. "The upregulation of BUB1B, CCNA2, and CCNB2 in pathway studies is associated with the development of Human T-cell leukemia virus 1 infection and Acute myeloid leukemia." (PMID 40100920, 2025). "Li found that microrNA-582-3p negatively regulates cell proliferation and cell cycle progression in acute myeloid leukemia Targeting cyclin B2." (PMID 35386287, 2022). "For example, it represses the growth and cell cycle progression of acute myeloid leukemia cells via inhibiting cyclin B2." (PMID 34898351, 2021). "Cyclin B2 (CCNB2) knockdown significantly suppressed cell proliferation and induced G2/M-phase arrest in acute myeloid leukemia cells." (PMID 35246013, 2022).
pituitary tumours (7 papers, 2012 to 2023). "Diurnal rhythm of PER2 parallels those of cell cycle genes (Ccnb2, Cdc20 and Espl1) in pituitary tumors, supporting PER2 as a driver of rhythmicity in these cell cycle genes and implicating a diurnal rhythm in cell cycle." (PMID 37215573, 2023). "HMGA-induced CCNB2 (a molecule of the cyclin clan) plays an important role in the development of mouse or human pituitary tumours." (PMID 31870357, 2019). "Most of the genes with consistently decreased expression were involved in mitotic cell cycle regulation (e.g., cyclin B2, pituitary tumor-transforming gene 1)." (PMID 23095216, 2012). "HMGA induces the overexpression of CCNB2 to promote the development of human pituitary tumours." (PMID 34838000, 2021).
adrenocortical carcinoma (6 papers, 2014 to 2022). "Cyclin B2 has been shown to be overexpressed in adrenocortical carcinoma and is thus a good candidate for distinguishing benign from malignant adrenocortical tumors." (PMID 25279464, 2014).
breast tumors (6 papers, 2011 to 2025). "We have shown a significant association of CCNB2 protein expression with breast tumor type, indicating that the CCNB2 protein levels were unevenly distributed among the histological types." (PMID 23282137, 2013). "The relative gene expression analysis of seven PGC-associated genes, including CCNB1, CCNB2, FEN1, MCM4, PTTG1, RACGAP1, and UBE2C, was conducted on the samples of breast tumors compared to healthy mammary tissues." (PMID 41009526, 2025). "Through integrative analyses of transcriptomic datasets, we identified a germline-associated molecular signature, with CCNB1, CCNB2, PTTG1, RACGAP1, and UBE2C emerging as core EGT gene clusters markedly upregulated in breast tumors." (PMID 41009526, 2025). "The average expressions of these genes in breast tumor samples compared to healthy mammary biopsies (tumor/healthy) were as follows: CCNB2 (0.483/−0.869), CCNB1 (0.262/−0.472), PTTG1 (0.398/−0.719), RACGAP1 (0.338/−0.609), and UBE2C (0.565/−1.016)." (PMID 41009526, 2025). "Pharmacological inhibition of ACK1 using its inhibitor, (R)-9b dampened CCNB1, CCNB2 and CDC20 expression, caused G2/M arrest, culminating in regression of palbociclib-resistant breast tumor growth." (PMID 37330596, 2023). "Regarding to the clinical relevance of our results, low expression levels of βArr1 were inversely correlated with CDC45, BUB1, CCNB1, and CCNB2 genes compared to normal tissue samples while positively correlated with poorer prognosis in breast tumours." (PMID 33452359, 2021). "TCGA data analysis also indicates the clinical relevance of our results, the low expression levels of βArr1 are inversely correlated with CDC45, BUB1, CCNB1, and CCNB2 genes compared to normal tissue samples while positively correlated with poorer prognosis in breast tumours." (PMID 33452359, 2021). "RT-qPCR detection confirmed the relationship of ALDOA with CDC45 and CCNB2 in breast tumors." (PMID 28191039, 2017). "The result of our experience has highlighted a significant overexpression of five CCNB1, CCNB2, PTTG1, RACGAP1, and UBE2C genes in breast tumors compared to the normal tissues (p-value < 0.05)." (PMID 41009526, 2025). "The expression levels and subcellular localization of the CCNB2, ASPM, CDCA7, KIAA0101, and SLC27A2 proteins were measured using immunohistochemistry (IHC) on a panel of 80 primary invasive breast tumors." (PMID 23282137, 2013). "We further detect transcripts of ALDOA and several hub genes in breast tumors by RT-qPCR, and Pearson’s correlation analysis demonstrated a positive relationship of ALDOA with CCNB2 and CDC45, but not CDC20 and TK1, even a trend observed between them." (PMID 28191039, 2017).
cervical cancer (6 papers, 2013 to 2024). A primary or metastatic malignant neoplasm involving the cervix. "CCNB2 has been scantly associated with cervical cancer; however, it has been reported to be associated with other types of cancer." (PMID 23405241, 2013). "Of the top 10 ranked upregulated genes, 2 have not been previously reported as associated with cervical cancer (NUSAP1, and CDKN3), while the other 8 have been associated with cervical cancer either scantly (SYCP2, PRC1, CCNB2 and CDC20) or widely (MKI67, CDKN2A, CDC2, and PCNA)." (PMID 23405241, 2013). "PRC1, CCNB2, and SYCP2 are markers exclusively associated with invasive cervical cancer." (PMID 23405241, 2013). "In this work we identified 6 genes (PRC1, CCNB2, SYCP2 CDKN3, NUSAP1, and CDC20) associated with invasive cervical cancer that could be used either as markers for diagnosis or as therapeutic targets." (PMID 23405241, 2013).
osteosarcoma (6 papers, 2012 to 2024). A usually aggressive malignant bone-forming mesenchymal neoplasm, predominantly affecting adolescents and young adults. "For instance, AURKA, MCM2 and CCNB2 which are among the prototypical genes showing overexpression in the most aggressive osteosarcomas were among the genes that were significantly reduced in OS cells treated with 5-AzadC and 4-PBA." (PMID 22957032, 2012). "STIL is associated with osteosarcoma proliferation and invasion, and may be promote the progression of osteosarcoma by regulating the expression of CDK1, CCNB2, CDC20, CCNA2, BUB1 and AURKB." (PMID 33858425, 2021). "In the PPI network, we selected six genes (CDK1, CCNB2, CDC20, CCNA2, BUB1, and AURKB) as the core STIL differentially co-expressed genes in osteosarcoma." (PMID 33858425, 2021). "Using the 13 gene chips, we found that six hub differentially co-expressed genes (CDK1, CCNB2, CDC20, CCNA2, BUB1, and AURKB) were highly expressed in osteosarcoma." (PMID 33858425, 2021). "KIAA1429 may contribute to the progression of osteosarcoma by targeting CDK1, CCNA2, and CCNB2, which make it possible to become a potential biomarker and therapeutic target of osteosarcoma." (PMID 38164289, 2024). "Moreover, the bioinformatics analysis showed that STIL may participate in the biological function of osteosarcoma by regulating CDK1, CCNB2, CDC20, CCNA2, BUB1, and AURKB." (PMID 33858425, 2021).